LEP (leptin)
Diseases named in the same sentence as LEP in open-access papers (continued):
Sharing a sentence is not in itself a finding about the gene and the disease.
Obesity (continued). "In humans, obesity is the result of lifestyle and multifactorial genetic inheritance, rather than leptin deficiency/resistance of monogenic inheritance, although obese T2DM patients often have abnormal levels of leptin, likely secondary to the development of T2DM." (PMID 24809394, 2014). "To explore a biological mediator for this association, we analyzed data and found that the strong association of obesity with OVC risk was attenuated (OR from 2.41 to 1.15) after adjustment of leptin levels, suggesting that the BMI effect may be explained by the high leptin levels in the OVC cases." (PMID 25115836, 2014). "Some probiotics are shown to exert anti-obesity impact by regulating lipid and glucose metabolism, generating conjugated linoleic acid, decreasing the size of adipocytes and augmenting the number of small adipocytes in white adipose tissue, and regulating leptin expression." (PMID 24475077, 2014). "Conversely, n-3 PUFA have been shown to improve the hypoxic AT microenvironment by reducing adipocyte size and to decrease obesity-associated expression of HIF-1α, thereby providing a mechanism through which local leptin signaling responsiveness could be attenuated." (PMID 25360510, 2014). "Because obesity can deregulate leptin signaling, an attractive explanation for our results is that a high-fructose diet in mice fails to cause obesity, and therefore no leptin resistance would be expected." (PMID 25211467, 2014). "Other possible explanations may be obesity affects the milieu of cytokines produced by adipose tissue during ischemia-reperfusion, such as leptin, which has been shown to be increased in patients with acute lung injury and play a role in the development of acute lung injury in animal model." (PMID 24658073, 2014). "Our results suggest that factors associated with obesity or with leptin signaling in non-myeloid populations such as natural killer and T cells may be associated with worsened outcomes following influenza A infection." (PMID 25232724, 2014). "Conversely, the fact that leptin is a pro-inflammatory cytokine secreted by adipocytes, in proportion to adipocyte mass, points to a role for leptin in obesity-associated inflammation and insulin resistance, and many have speculated on the role for leptin in promoting inflammation in obesity." (PMID 25157251, 2014). "Obesity can be a cause of leptin resistance, but a lack of sensitivity to circulating leptin may also induce obesity." (PMID 24886049, 2014). "However, leptin deficiency disables host defense, in the absence of obesity, and has been demonstrated to restore antimicrobial functions in the presence of obesity in ob/ob mice." (PMID 25203099, 2014). "Therefore, leptin may upregulate the expression of GRP78, thereby protecting against ER stress associated with obesity." (PMID 25403445, 2014). "Furthermore, recent studies have shown that induction of inflammation in the hypothalamus results in experimental obesity, resistance to the anorexigenic hormone leptin, peripheral insulin resistance and defective regulation of food intake and energy expenditure." (PMID 24675731, 2014). "Our results further demonstrated that plasma leptin levels were also independently and positively associated with NMD in both lean and overweight subjects and those associations were found only after adjusting for other confounders including age, obesity, BP, and lipids." (PMID 24410779, 2014). "However, increased tissue expression due to other pathological conditions than muscular dystrophy, such as aging, obesity and treatment with insulin or leptin, might affect serum levels of CA3." (PMID 24920607, 2014). "While altered peripheral metabolism, deficits in neural signaling, and leptin resistance are all contributors to chronic over-consumption and obesity in this model, impaired oral and post-oral feedback likely play an important role in the development of obesity." (PMID 25329959, 2014).
Obesity (continued). "Another factor involved could be leptin, a peptide hormone secreted by adipocytes, which has been shown to be increased in hypertensive patients even after adjustment for major confounders, including obesity." (PMID 24499246, 2014). "Extreme obesity due to impaired leptin signaling in mice does not cause knee osteoarthritis." (PMID 25184806, 2014). "Similarly, these studies are of limited use, if any, for characterizing signaling cascades associated with human obesity since deficiencies in leptin signaling cascades do not significantly influence human obesity." (PMID 24809394, 2014). "In addition, we investigated whether the impairment of acute NO-mimetic effect of leptin in obesity was accounted for by chronic hyperleptinemia." (PMID 24475175, 2014). "However, in the early phase of obesity when insulin sensitivity is not impaired, total vasodilating effect of leptin is intact because NO deficiency is compensated by EDHF." (PMID 25521118, 2014). "Therefore, leptin is emerging as a major contributor to the hypertensive state observed in obesity." (PMID 25152707, 2014). "Therefore, leptin resistance is a major factor in the development of obesity." (PMID 24421337, 2014). "Thus genetic variation may have effect on methylation percentages and subsequently on the regulation of leptin gene expression which may lead to obesity in these obese mutant rat strains." (PMID 24495350, 2014). "Instead, leptin, an adipose-derived hormone that increases in obesity may be involved." (PMID 25309539, 2014). "In PCOS, leptin resistance results not only in insufficient permissive signaling to achieve optimal LH pulse secretion, but also in defective suppression of appetite, which may perpetuate obesity." (PMID 25763405, 2014). "In addition, leptin also activates transcription factors, leading to activation of protein-1 and NF-κB in endothelial cells, accelerating atherogenic processes and contributing to development of vascular pathology in obesity." (PMID 24025484, 2013). "Adipose tissue hypoxia (ATH) may provide cellular mechanisms for the development of insulin resistance, chronic inflammation, macrophage infiltration, adiponectin reduction, leptin elevation, adipocytes death, ER stress, and mitochondrial dysfunction in white adipose tissue in obesity." (PMID 23819063, 2013). "Therefore, obesity is characterized as a “leptin resistant state”." (PMID 24202338, 2013). "In contrast to mutant leptin-lacking ob/ob mice, a link between human obesity, often associated with high serum leptin and SERT regulatory cascades leading to its reduction or internalization can be hypothesized." (PMID 24138674, 2013). "Moreover, the excessive secretion of leptin and/or decreased production of adiponectin by adipocytes in obesity may either directly affect bone formation or indirectly affect bone resorption through upregulated proinflammatory cytokine production." (PMID 24302863, 2013). "Our findings also suggest that hearts from diet-induced obese mice continue to respond to leptin in the presence of chronically elevated leptin levels and that the observed elevation of serum and cardiac leptin may thus contribute to the development of cardiac hypertrophy in obesity." (PMID 23841921, 2013). "In addition to the oestrogen-hypothesis, it has been suggested that adipose derived hormones such as leptin and adiponectin play a significant role in the asthma-obesity relationship." (PMID 24204876, 2013). "Furthermore, the leptin concentration was a predictor factor to explain changes in lung function, demonstrating the role of this adipokine in the inflammatory process, linking obesity and pulmonary disorders." (PMID 24285955, 2013). "How leptin resistance develops and how it could be treated in obesity is now under investigation." (PMID 24288531, 2013).
Obesity (continued). "Therefore, leptin may represent an essential nutrient during lactation in protection against obesity and related disorders in later life, and may also be considered a strategy for the reversion of prenatal adaptations resulting from fetal undernutrition." (PMID 24062695, 2013). "Previous in vitro and in vivo studies conducted by our group demonstrated an impaired leptin-dependent signal transduction in natural killer (NK) cells in diet-induced obesity (DIO) which could be ameliorated by transfer of NK cells to a normal-weight metabolic environment." (PMID 24098717, 2013). "In obesity-related high plasma leptin conditions, inflammation occurs when signal transduction pathways are activated, such as activation of NFκβ, by the binding of leptin to its receptor (Ob-R), and subsequent release of the inflammation factors, for instance tumour necrosis factor alpha (TNFα)." (PMID 23856194, 2013). "Leptin, an adipocyte-secreted protein related to obesity, may play a role in learning and memory." (PMID 23570390, 2013). "However, it is not known yet if supraphysiological doses of thyroid hormones together with either obesity or a calorie restriction diet might increase DNA damage, oxidative stress, insulin resistance and serum leptin concentration." (PMID 23468891, 2013). "The role of oestrogen, leptin, adipokine, genes and epigenetics should be further investigated, as these features might play an important role in the relationship between sex, asthma and obesity." (PMID 24204876, 2013). "The discovery of leptin in 1994 brought about an entirely new physiological system with direct implications for the pathophysiology of human obesity and has helped develop treatments for obesity as well as other metabolic conditions, such as diabetes (see review)." (PMID 23557393, 2013). "Hypothesis, we found lower levels of circulating leptin in Inuit children compared to Danish children despite Inuit children having a more unfavourable metabolic profile, including higher prevalence of overweight and obesity." (PMID 23940841, 2013). "This inhibition of leptin secretion by adipocytes may alter the cellular fat reserve, which potentially has implication for conditions within the metabolic syndrome spectrum including obesity and type-2-diabetes." (PMID 23544120, 2013). "Hence, these observations suggest that leptin resistance in β-cells may contribute to obesity-related diabetes." (PMID 23936486, 2013). "Considering the literature, two hypotheses have received considerable attention concerning the occurrence of leptin resistance during the development of obesity: 1) failure of circulating leptin to reach its central targets and 2) impaired intracellular leptin signaling." (PMID 24039946, 2013). "Also, studies have shown an increased inflammatory response associated with the presence of hyperleptinemia without obesity, and that leptin is able to control TNF-α production and activation by macrophages." (PMID 23593289, 2013). "Similarly, both leptin and insulin receptor expression is decreased within the CNS in obesity." (PMID 23550218, 2013). "Obesity is also associated with BMD because of the conversion of androgen to estrogen, which improves bone mass in both men and women and maintains healthy plasma levels of insulin and regulating factors including insulin-like growth factor-1, leptin, and adiponectin." (PMID 24222888, 2013). "Hence, they may be involved in the pathogenesis of obesity and the role of some of them (leptin, adiponectin, resistin, and visfatin) has been extensively studied in the disease." (PMID 24376307, 2013). "Overexpression ↑ diurnal overeating, BW, obesity; associated with elevated circulating leptin and dysfunctional adipocytes with no changes in POMC immunoreactivity; knockdown did not affect basal feeding or weight gain but ↓ fasting-induced hyperphagia and locomotion." (PMID 24385950, 2013).
Obesity (continued). "In addition, leptin has a permissive role in initiating puberty and is crucial in the pathogenesis of reproductive dysfunction in several disease states of energy imbalance, such as anorexia on one side, and obesity on the other." (PMID 23544111, 2013). "Leptin resistance would appear to affect multiple neural and endocrine pathways that affect emotions and mood including hippocampal and mesolimbic dopamine pathways and HPA activity, and thus represents another strong candidate mechanism underlying depression in obesity." (PMID 24109426, 2013). "Thus, it is reasonable to speculate that the activation of I1R by allantoin may mediate leptin to inhibit hypothalamic NPY for reduction of hyperphagia to result in the decrease of obesity." (PMID 23606885, 2013). "Some probiotics have been demonstrated to have an anti-obesity property by regulating lipid and glucose metabolism, producing conjugated linoleic acid, reducing the adipocyte size and increasing the number of small adipocytes in white adipose tissue, and regulating leptin." (PMID 23382926, 2013). "Thus, it is unclear whether the cardiac hypertrophy in obesity is the consequence of pro-hypertrophic effects of the adipokine or rather the result of a resistance towards leptin’s preventive effects on hypertrophic cardiac remodeling." (PMID 23841921, 2013). "Therefore, high levels of leptin are essential in linking obesity to allergic airway inflammation." (PMID 23773659, 2013). "Thus, a greater knowledge of CNTF-mediated regulation of the energy balance may suggest new therapeutic strategies for human leptin-resistant obesity." (PMID 24409114, 2013). "Thus, the role of the adipokine in mediating cardiac hypertrophy, in particular in the presence of elevated systemic leptin levels, and the possible existence of a cardiac leptin resistance in obesity remains unclear." (PMID 23841921, 2013). "However, resistance to these normal actions of leptin have been demonstrated in obesity." (PMID 24312178, 2013). "The influence zinc has on the adipocyte through the expression of leptin, by promoting free fatty acid release and glucose uptake, may also be controlled through the expression of a number of zinc-transporters in the adipocyte, that may be altered in obesity." (PMID 22703731, 2012). "Increased circulating leptin, a marker of leptin resistance in obese Down children seems to be similar to that in children with simple obesity, this could point to an absence of genetic basis for more leptin resistance in such high risk population for obesity." (PMID 23067442, 2012). "However, when stratifying by BMI and percent body fat, a negative association was found between zinc and leptin concentrations in women with obesity, with a body fat content of 36-40% and high waist circumference." (PMID 22703731, 2012). "On the other hand, leptin-deficient mice carrying an homozigous mutation disrupting leptin gene (ob/ob mice) are hyperphagic, show lower energy expenditure at rest, and are less active, and then show a severe form of obesity due to the lack of leptin signalling to the brain." (PMID 22235202, 2012). "Like other indices of obesity (BMI, waist:hip ratio) leptin was not related to sST2 levels following adjustment for age and sex (p = 0.066); the negative univariate association between leptin and sST2 was explained by an association between leptin and sex." (PMID 23112853, 2012). "Elevated plasma leptin levels in obesity may contribute to cancer incidence." (PMID 22853725, 2012). "Notably, leptin administration is effective in treating obesity." (PMID 22474595, 2012). "Furthermore, we postulate that the elevated levels of leptin found in obesity, T2DM, and MetS may collaborate with UA and contribute to tumorigenesis and metastasis by down regulation of tumor cell XOR." (PMID 23369448, 2012).
Obesity (continued). "In the United States population, increased leptin concentrations was significantly associated with increased risk of myocardial infarction and stroke in men and women, independent of traditional cardiovascular risk factors and obesity status." (PMID 22642879, 2012). "There is also some evidence that leptin may have a role in obesity-related hypertension." (PMID 22642879, 2012). "Insulin and leptin levels were significantly lower, and adiponectin levels were higher in the two meals per day group than in the FF group, suggesting that restricted feeding with two meals a day is remarkably effective for protecting against obesity and metabolic syndrome." (PMID 22587351, 2012). "Leptin, a hormone affecting appetite and obesity, may also influence bone mass, although it is not clear whether leptin is negatively associated with bone mass." (PMID 23300848, 2012). "Leptin, an anorexic hormone, secreted by adipose tissue, binds to the appropriate leptin receptor triggering intracellular signaling processes in the ventromedial hypothalamus (satiety center) which in turn provides a negative feedback system to inhibit caloric intake and prevent obesity." (PMID 22988521, 2012). "A lack of leptin signalling due to mutation of leptin (ob/ob) or the leptin receptor (db/db) in mice and in humans results in an increase of food intake concomitant with a reduction of energy expenditure and leads to severe obesity." (PMID 22291999, 2012). "In addition, in abnormal situations that are characterized by chronic hyperleptinemia such as obesity, leptin may function pathophysiologically in the development of hypertension and possibly in direct renal, vascular, and cardiac damage." (PMID 22848362, 2012). "In this regard, obesity is also a neurobehavioral disorder, with the coupling of energy intake and expenditure being tightly regulated by hypothalamic factors, the hypothalamus mediating exercise-induced appetite suppression, and exercise sensitizing the hypothalamus to leptin and insulin." (PMID 22808000, 2012). "Thus, insulin and/or leptin resistance in skeletal muscle may play a significant role in the pathogenesis of obesity and type 2 diabetes." (PMID 23115649, 2012). "Thus, it has been postulated that while leptin and leptin receptor signaling act to suppress food intake and maintain long-term energy balance, the excess serum leptin found in obesity may reflect a state of leptin resistance." (PMID 23369448, 2012). "They used leptin-deficient ob/ob mice and high-fat diet (59% fat, 15% protein, 26% carbohydrate)-induced obesity models and found that diethylnitrosamine-induced hepatocellular carcinoma (HCC) is significantly advanced in the both of these murine obesity models." (PMID 22853690, 2012). "Therefore, obesity leads to an increase in the circulating leptin levels." (PMID 22778500, 2012). "Other genes such as MC4R, leptin and leptin receptor, Ghrelin (GHRL), peroxisome proliferator-activated receptor gamma (PPARG), oxytocin receptor (OXTR), prohormone convertase-1 and proopiomelanocortin have been implicated in human obesity and will be discussed elsewhere in this journal issue." (PMID 22043167, 2011). "It appears that leptin may be an important factor in obesity management." (PMID 21745411, 2011). "A hypothesis to reconcile this unexpected observation is that IL-1α is a homeostatic regulator that opposes excess positive energy balance, wherein elevated IL-1α levels in obesity reflect inadequate compensation, analogous to what occurs with the adipokine leptin." (PMID 22216303, 2011). "It has been hypothesized that loss of functioning ALMS1 could impact the cilia on hypothalamic neurons and lead to alteration in behavior and energy homeostasis, through abnormal perception of appetite and satiety cues, such as leptin, resulting in overeating and obesity." (PMID 22043170, 2011).